LMNB1 (lamin B1)
Diseases named in the same sentence as LMNB1 in open-access papers (continued):
Sharing a sentence is not in itself a finding about the gene and the disease.
laminopathies (continued). "While many laminopathies are associated with mutations in LMNA gene, only two have been associated with alterations in lamin B: the autosomal dominant leukodystrophy and the acquired partial lipodystrophy caused by LMNB1 and LMNB2 mutations, respectively." (PMID 33369245, 2021). "We identify dominant pathogenic variants in LMNB1 and LMNB2 as a genetic cause of primary microcephaly, implicating a major structural component of the nuclear envelope in its etiology and defining a new form of laminopathy." (PMID 33033404, 2021). "Since no obvious differences in resolution between these methods were found in either confocal and STED microscopy, we used immunofluorescence labeling for determining the colocalization between lamin A/C and lamin B1 in a cell culture of laminopathy patient dermal fibroblasts." (PMID 34638534, 2021). "Consistent with previous reports that aged iPSCs display nuclear lamina alterations reminiscent of those observed in laminopathies and cellular senescence, we found that Lamin B1 invaginations increased with iPSC passage number in both control and C9orf72 iPSNs." (PMID 33741069, 2021). "In addition to the laminopathies caused by loss-of-function mutations, disease and changes in cultured cells are associated with overexpression of both LMNA and LMNB1." (PMID 17565385, 2007). "Taken together, the decrease in Lamin B1 in our in vitro models, fresh PBMCs from the segmental duplication case, and various DS foetal tissues lead us to hypothesise that DS contains a strong B-type laminopathy component." (PMID 37451904, 2023). "Counterstaining with Lamin B1 in Lamin A/C-depleted cells and Lamin A/C upon Lamin B2 Kd revealed distorted nuclear shapes, nuclear invaginations, blebbing, and nuclear furrows as found in Lamin A/C- and B1-depleted HeLa cells and in cells derived from laminopathies." (PMID 26921073, 2017). "Finally, further studies are needed to detangle particular roles of individual lamins (lamin A, lamin C, lamin B1, and B2) and better understand the cell requirements in terms of migration, differentiation, and cell senescence and provide further insight into the pathology of laminopathies." (PMID 29750601, 2018). "mir‐351 has also been described to modulate lamin B1 expression using an F28‐7 cell model not related to laminopathy (a clone of mouse mammary carcinoma FM3A)." (PMID 29696758, 2018).
lung carcinoma (17 papers, 2017 to 2025). "Loss of lamin B1 plays a key role in lung cancer and it has been demonstrated that lamin B1 levels were decreased in patients of lung cancer." (PMID 32321983, 2020). "Here we report that loss of lamin B1, a determinant of nuclear architecture, plays a key role in lung cancer." (PMID 31015297, 2019). "Lamin B1 loss promotes lung cancer development and metastasis by loss of PRC2 recruitment to chromatin and activation of the RET/p38 signaling axis." (PMID 31015297, 2019). "In addition, epigenetic effects of lamin B1 were suggested to cause its inhibitory effect on lung cancer cell migration." (PMID 32987785, 2020). "Importantly, RET levels negatively correlate with lamin B1 levels in lung cancer patients, supporting a link between lamin B1 loss and RET upregulation." (PMID 31015297, 2019). "Together, these findings support the notion that loss of lamin B1 may play a role in promoting lung cancer initiation, progression, and malignancy." (PMID 31015297, 2019). "Moreover, a higher Lamin B1 expression level has been linked to increased cancer aggressiveness, such as in liver and pancreatic cancer, while in contrast, lower Lamin B1 is associated with poor prognosis and more aggressiveness in breast and lung cancers." (PMID 39727946, 2024). "Analysis of TCGA data indicates that in human lung tumors LMNB1 is rarely affected by point mutations but lies within a relatively large region of recurrent deletion (data not shown), which may contribute to a decrease in LMNB1 levels in lung cancer." (PMID 31015297, 2019). "A role for lamin B1 in regulating the epigenetic mechanisms of tumor cells has been elucidated in lung cancer." (PMID 39866838, 2025). "Specifically, the loss of lamin B1 reactivated the proto‐oncogene RET, thus facilitating EMT, tumor proliferation, and enhanced cell migration in lung cancer cell lines." (PMID 39866838, 2025). "Lamin B1 is overexpressed in lung adenocarcinoma cells and promotes the proliferation of lung cancer cells via the AKT pathway." (PMID 35805937, 2022). "From this perspective, lamin B1 plays a key role in lung cancer progression, providing a molecular link between altered nuclear morphology, aberrant epigenetic patterning, and malignant phenotype." (PMID 35132494, 2022). "Lamin B1 (LMNB1), under-expressed in both cell lines in our study, has been described as a tumor suppressor in lung cancer." (PMID 36011023, 2022). "Higher LMNB1 mRNA expression in lung cancer cells, with respect to normal tissues, was related to tumor stage and adverse overall survival, while LMNB1 knock down inhibited lung cancer cell proliferation." (PMID 36005596, 2022). "Lower levels of lamin B1 expression, indeed, in patients affected by lung cancer favour metastasis through epigenetic mechanism." (PMID 35132494, 2022). "The role of Lamin B1 in lung cancer has been previously explored, and it has also been reported that LMNB1 is downregulated during senescence in IMR90 cells." (PMID 32055858, 2020). "We found that lamin B1 levels were reduced in lung cancer patients and that lower lamin B1 expression correlated with higher lung cancer grade." (PMID 31015297, 2019). "In this study, we describe a crucial function of lamin B1 in lung cancer development and progression." (PMID 31015297, 2019). "An intriguing question that needs further investigation concerns the upstream mechanisms leading to lamin B1 downregulation in lung cancer patients." (PMID 31015297, 2019). "The depletion of lamin B1 induced significant alterations in the H3K27me3 landscape, revealing a connection between both aberrant nuclear architecture and epigenetic patterning and the aggressiveness of lung cancer." (PMID 39866838, 2025). "The researchers suggested that LMNB1 acted as a tumor suppressor in lung cancer." (PMID 38824174, 2024).
lung carcinoma (continued). "In summary, we suggested for the first time that EIF3C is upregulated in lung cancer tissues and may enhance the proliferation and suppress the apoptosis of lung cancer cells by regulating the APP/HSPA1A/LMNB1 axis." (PMID 36157221, 2022). "EIF3C overexpression may facilitate the proliferation and hamper the apoptosis of lung cancer cells by regulating the APP/HSPA1A/LMNB1 axis." (PMID 36157221, 2022). "However, analyses of cancer cell migration identified a migration inhibitory role for lamin B1 in lung cancer cells, while a migration promoting activity was found for lamin B1 in pancreatic cancer cells." (PMID 32987785, 2020). "Thus, lamin B1 acts as a tumor suppressor in lung cancer, linking aberrant nuclear structure and epigenetic patterning with malignancy." (PMID 31015297, 2019). "Importantly, loss of lamin B1 led to EMT and strongly promoted migration and invasion of mouse and human lung epithelial cells as well as lung cancer cell lines both in culture and in vivo." (PMID 31015297, 2019). "Thus, lamin B1 plays a key role in lung cancer development and progression, providing a molecular link between altered nuclear morphology, aberrant epigenetic patterning, and the malignant phenotype." (PMID 31015297, 2019). "In our paper, we uncover a key function of lamin B1 as a tumor suppressor in lung cancer." (PMID 31015297, 2019). "Inhibition of p38, similarly to RET inhibition, decreased the highly migratory phenotype of lamin B1–depleted lung epithelial cells and lung cancer cells, supporting the notion that activation of the RET/p38 signaling axis mediates the increased migratory and invasive phenotype upon lamin B1 loss." (PMID 31015297, 2019). "We found that lamin B1 levels were reduced in lung cancer patients." (PMID 31015297, 2019). "Importantly, the RET expression in the tumors negatively correlated with the lamin B1 expression, supporting a link between lamin B1 loss and RET upregulation in lung cancer patients." (PMID 31015297, 2019). "Consistently with this, in lamin B1–depleted cells we observed binding of the Ret promoter by the transcription factor Ascl1, which has been shown to directly activate Ret expression and play an important role in lung cancer development." (PMID 31015297, 2019). "On the other hand, lamin B1 is a promising biomarker for later stages of lung cancer." (PMID 29285216, 2017). "Our findings revealed that in lung cancer tissues or cells, five transcription factors—FOXA1, CEBPB, CTCF, LMNB1, and POLR2A—concurrently regulate the transcription of COL5A1, MMP1, and SERPINE1." (PMID 39551792, 2024). "The increased expression levels of LMNB1 can enhance cell migration potential, which may contribute to the progression and metastasis of some cancers, including pancreatic cancer (PC), prostate cancer, lung cancer, hepatocellular carcinoma (HCC), and kidney cancer." (PMID 38824174, 2024). "Thus, we speculated that EIF3C may play a carcinogenic role in lung cancer by regulating LMNB1." (PMID 36157221, 2022). "To analyze whether there is a correlation between lamin B1 and RET levels in lung cancer patients, we analyzed RET expression in a human lung tissue microarray." (PMID 31015297, 2019). "However, there is currently no clear picture emerging especially for the role of lamin B1 in lung cancer, which was reported to have either oncogenic or tumor-suppressive functions." (PMID 38067205, 2023).
pancreatic cancer (17 papers, 2009 to 2024). "For example, Lamin B1 was reported to overexpressed in pancreatic cancer vs. normal pancreas, and high Lamin B1 expression was associated with less differentiated tumors and shorter patient survival." (PMID 34685604, 2021). "This study is consistent with a finding that over-expression of lamin B1 is associated with low grade differentiation in pancreatic cancer and that the drug betulinic acid down-regulates lamin B1 expression as part of its anti-cancer activity." (PMID 24380701, 2014). "To date, numerous studies have reported that LMNB1 is dysregulated in different cancers, including colorectal cancer, clear-cell renal carcinoma, pancreatic cancer and gastric cancer." (PMID 35436411, 2022). "On the contrary, the decrease of lamin B1 reduces the proliferation, invasion, and tumorigenicity of pancreatic cancer cells." (PMID 35132494, 2022). "For example, overexpression of LMNB1 in pancreatic cancer cells greatly enhances anchorage-independent growth and migration abilities by targeting Sp1 transcription factor (Sp1)." (PMID 35436411, 2022). "For instance, increased Lamin B1 level in pancreatic cancer has been correlated with poor prognosis, and Lamin B1 has been proposed as a therapeutic target." (PMID 33918867, 2021). "Previous studies showed that LMNB1 was overexpressed in pancreatic cancer, liver cancer and prostate cancer and its overexpression was associated with poor clinical outcomes in the cervical and colon cancers." (PMID 33796525, 2021). "Further, in this study, depletion of Lamin B1 decreased pancreatic cancer cell growth in vitro and in xenografts in mice." (PMID 34685604, 2021). "In pancreatic cancer cell models, lamin B1 knockdown significantly diminished proliferative aggressiveness and invasiveness." (PMID 31867128, 2018). "Lu et al29 found that S100PBP may inhibit pancreatic cancer cell adhesion through the LMNB1 and PRKRA gene pathways." (PMID 39128058, 2024). "For this reason, it has been suggested that the increase of lamin B1 could be considered as a novel biomarker for pancreatic cancer and as a therapeutic target." (PMID 35132494, 2022). "Sp1 has been noted to transcriptionally upregulate lamin B1 in pancreatic cancer." (PMID 36615262, 2022). "Lamin B1 overexpression contributed to invasion of pancreatic cancer cells." (PMID 36615262, 2022). "Indeed, the knockdown of Lamin B1 significantly attenuated the proliferation, invasion, and tumorigenicity of pancreatic cancer cells." (PMID 33918867, 2021). "In addition, the silencing of LMNB1 impaired tumorigenicity, tumor invasion, and cell proliferation in pancreatic cancer cells." (PMID 32149105, 2020). "Depletion of Lamin B1 inhibited the proliferation and invasion of pancreatic cancer cells." (PMID 27503760, 2016). "Importantly, lamin B1 inhibition significantly attenuated tumor growth of pancreatic cancer cells." (PMID 36615262, 2022). "Our study identified the known S100A6-binding proteins, tropomyosin β, annexin 11 and annexin 2 as well as novel binding protein lamin B1, as candidate S100A6 interactors in pancreatic cancer cells." (PMID 19724273, 2009). "Moreover, by analysing transcriptomics and proteomics datasets of human PDAC, we found that Slc3a2 and Lamin B1 were significantly elevated in PDAC tissue when compared to the normal tissue counterpart, thus indicating a positive role of these genes in pancreatic cancer progression." (PMID 39587609, 2024).
Adult-onset autosomal dominant leukodystrophy (16 papers, 2012 to 2026). "For example, autosomal-dominant adult-onset demyelinating leukodystrophy (ADLD) is caused by overexpression of LMNB1 protein usually attributed to duplication of the LMNB1 gene." (PMID 38436667, 2024). "Adult-onset Autosomal Dominant Leukodystrophy (ADLD) is characterized by accumulation of lamin B1 caused by tandem duplications involving the LMNB1 gene or deletions upstream of the LMNB1 gene." (PMID 35132494, 2022). "A heterozygous tandem genomic duplication of LMNB1 is known to be the cause of autosomal dominant adult-onset demyelinating leukodystrophy." (PMID 33584783, 2020). "Another type of leukodystrophy, adult-onset autosomal dominant leukodystrophy (ADLD) is characterized by duplication of the gene that codes for lamin B1 (LMNB1), which leads to overexpression of LMNB1 and causes severe myelin loss." (PMID 31614602, 2019). "In contrast to LMNA, coding mutations in LMNB1 have not so far been associated with human disease, although genomic duplication of LMNB1 is thought to cause a progressive demyelinating disorder, adult-onset autosomal dominant leukodystrophy." (PMID 23166514, 2012). "Conversely, defects in B-type lamins are rare events and reported in some genetic diseases as the adult-onset autosomal dominant leukodystrophy (ADLD) associated to LMNB1 duplication or LMNB1 promoter mutation, and the partial lypodystrophy associated to LMNB2 heterozygous mutations." (PMID 32069980, 2020). "Chromosomal rearrangements with duplication of the lamin B1 (LMNB1) gene underlie autosomal dominant adult-onset demyelinating leukodystrophy (ADLD), a rare neurological disorder in which overexpression of LMNB1 causes progressive central nervous system demyelination." (PMID 25701871, 2015). "Adult-onset autosomal dominant leukodystrophy (ADLD) is a rare, slowly progressive, and fatal neurodegenerative disorder characterized by central nervous system white matter loss due to LMNB1 gene abnormalities encoding laminB1." (PMID 40046440, 2025). "Adult-onset autosomal dominant leukodystrophy (ADLD) is a rare, slowly progressive, and fatal neurodegenerative disorder characterized by the loss of central nervous system (CNS) white matter, caused by either LMNB1 duplications or heterozygous deletions upstream of the LMNB1 promoter." (PMID 40046440, 2025). "Also, the Adult-Onset-Autosomal Dominant Leukodystrophy (ADLD), a central demyelination neuropathy, is produced by a heterozygous tandem genomic duplication of the Lamin B1 gene (LMNB1), codifying for another component of the nuclear lamina." (PMID 35327648, 2022).
hepatocellular carcinoma (14 papers, 2013 to 2024). A malignant tumor that arises from hepatocytes. "Proteomic-wide profiling of the plasma of hepatocellular carcinoma (HCC) patients found that LMNB1 was significantly upregulated and associated with tumor size and stage." (PMID 36005596, 2022). "The expression of LMNB1 was significantly up-regulated in the plasma and tissue of hepatocellular carcinoma patients, and it was associated with tumor stages, tumor sizes, and number of nodules." (PMID 24369726, 2013). "For example, LMNB1facilitates cell proliferation, EMT, and metastasis in hepatocellular carcinoma, LMNB1 promotes lung adenocarcinoma cell proliferation through the AKT pathway." (PMID 37041721, 2023). "Abdelghany A.M., Rezk N.S., Osman M.M., Hamid A.I., Al-BreedyA.M., Abdelsattar H.A. Using Lamin B1 mRNA for the earlydiagnosisof hepatocellular carcinoma: a cross-selectional diagnosticaccuracy study." (PMID 35342861, 2022). "LMNB1 is also discussed as a useful biomarker detecting hepatocellular carcinoma (HCC) in early stages." (PMID 35883595, 2022). "Furthermore, proteomic analysis indicated that lamin B1 is significantly upregulated in hepatocellular carcinoma tissue and is circulating in the plasma of corresponding patients, which can be useful for the detection of early stages of liver cancer." (PMID 35328162, 2022). "Lamin B1 levels are significantlyincreased in patients with hepatocellular carcinoma." (PMID 35342861, 2022). "Laminin B1 (LMNB1) (1.6 fold overexpressed; p-value ≤ 0.05) which is targeted by both miR-200b-3p and miR-200c-3p (downregulated in smoke exposed cells) is reported to be overexpressed in colorectal and hepatocellular carcinoma." (PMID 29728663, 2018). "In summary, this study identified two novel targets and provided new insight into mechanisms underlying anti-HCC effect of Huaier, revealing that Huaier restrained proliferation and cell motility of human hepatoma cell line SKHEP-1 partially via regulation of Lamin B1/NOV." (PMID 27503760, 2016). "The studies showed that lamin B1 is overexpressed in hepatocellular carcinoma (HCC) and positively correlates with tumor stage, size and number of tumor nodules in HCC patients." (PMID 32471220, 2020). "However, it is positively upregulated in hepatocellular carcinoma correlating with the TNM stage, while in renal clear cell carcinoma high LMNB1 levels exhibited poor prognosis." (PMID 38175424, 2024).